EGFR (epidermal growth factor receptor)
Diseases named in the same sentence as EGFR in open-access papers (continued):
Sharing a sentence is not in itself a finding about the gene and the disease.
tumor (continued). "Mutated EGFR are usually constitutively active, ligand-independent receptors with altered trafficking and down-regulation, resulting in aberrant downstream signal transduction which promotes tumour development." (PMID 32823532, 2020). "However, further mechanism studies should be sponsored for investigating the relationship between tumor metabolic activity and EGFR mutations." (PMID 32742498, 2020). "Interestingly, we report a case of EGFR variant selection, observed both upon tumor relapse in patients as well as upon xenografting." (PMID 33009951, 2020). "The concurrent existence of PDL1 expression and high levels of CD8+ tumor infiltrating lymphocyte (TILs) were only present in a small group of EGFR mutant tumors, suggesting an underlying mechanism of anti-PD1/PDL1 resistance in patients with EGFR or ALK mutation." (PMID 32793604, 2020). "It is possible that patients with tumor EGFR mutations who exhibit disease progression after first-line therapy may benefit from PD-1 inhibitors plus chemotherapy." (PMID 33102221, 2020). "Both patients with tumor EGFR mutations in the monotherapy group exhibited disease progression." (PMID 33102221, 2020). "In addition, our work shows molecular details about the tumor-promotion effect of WWP1 by inducing K63-linked K689 ubiquitination of EGFR, which subsequently promotes EGFR recycling and maintains EGFR stability." (PMID 32694521, 2020). "Currently, the first-line systemic treatment for advanced-stage NSCLC is targeted therapy for those who bear driver oncogene mutations in tumor, for example, epidermal growth factor receptor (EGFR) tyrosine kinase inhibitors (TKIs) for patients with drug-activating mutations in the EGFR gene." (PMID 33266057, 2020). "In 7 patients, an activating EGFR mutation was found in tumour DNA prior to inclusion." (PMID 32804306, 2020). "Our data suggest that sampling either the primary (pre- or posttherapeutical tumor tissue) or metastatic lesion may be valid for the initial evaluation of KRAS mutation status predicting the response to anti-EGFR treatment and guiding clinical decisions." (PMID 33002027, 2020). "Moreover, inhibition of GBM cells by EGFR is associated with anti-angiogenic and pro-apoptotic effects on the tumor." (PMID 32045997, 2020). "Additionally, we found a significant association between PFS and tumor genotype, patient sex, and vitamin D status, where EGFR mutation, female sex, and 25(OH)D3 >30 ng/mL directly associated with PFS." (PMID 32183160, 2020). "EGFR hotspot mutations activate the EGFR pathway and promote tumor cell proliferation." (PMID 32277151, 2020). "The 729 diagnostic tumor samples that were evaluated with the smMIP panel showed 788 (likely) pathogenic mutations, including mutations that give access to targeted treatment options (e.g. mutations in EGFR, BRAF, MET, ERBB2, KIT, PDGFRA)." (PMID 32264863, 2020). "Additionally, EGFR variants have been widely reported in various tumor types and related to tumor progression." (PMID 33261131, 2020). "The fact that EGFR seems to be implicated in tumor resistance to chemo/radiotherapy via activation of DNA DSB repair pathways such as non-homologous end joining (NHEJ) mechanism might also explain the reversibility of Rck-induced DNA-damage." (PMID 33330131, 2020). "The previous study identified EGFR tyrosine kinase domain mutations were identified and suggested that the role of EGFR as a growth factor receptor might be essential in tumor growth via tyrosine kinase signaling activity." (PMID 32033355, 2020). "EGFR overexpression is thought to be associated with large tumour size and poor clinical outcomes." (PMID 33144882, 2020).
tumor (continued). "In summary, the present study showed that East Asian NSCLC patients harboring EGFR L858R mutations were associated with an inflammatory tumor microenvironment, which may result in superior patient response to PD-1 inhibitors." (PMID 32944405, 2020). "A companion diagnostic test to detect epidermal growth factor receptor (EGFR) mutations in the circulating tumor DNA (ctDNA) of patients with non-small cell lung cancer (NSCLC) who may benefit from targeted therapy with erlotinib and osimertinib." (PMID 37361495, 2020). "While delE709-T710insD has been reported as a sole EGFR mutation, over 75% of substitutions at E709 are reported as “complex mutations” with the presence of additional EGFR mutations such as L858R, Ex19Del, or G719X detected within the same tumour." (PMID 31562956, 2020). "Adequate tumour samples were obtained from 93.0% (66/71) rebiopsy and 94.0% (126/134) initial biopsy patients for EGFR mutation analysis (p = 0.765), and from 100% (8/8) rebiopsy and 99.1% (122/123) initial biopsy patients for ALK rearrangements analysis (p = 1.000)." (PMID 32907572, 2020). "Abolishment of their activities through TKIs may inhibit tumor growth and lead to tumor shrinkage and complete response in some of the patients with EGFR mutations." (PMID 32923394, 2020). "If the number of tumor cells ≥100, it met the pathological quality control standard, and it could be used for subsequent EGFR gene mutation detection." (PMID 33357312, 2020). "EGFR overexpression or overactivation can result from mutations locking the receptor in a state of continual signaling or from abnormally high levels of EGFR ligands released from tumor cells or non-tumor cells of the tumor microenvironment." (PMID 31936715, 2020). "Aside from the immune infiltration, tumors’ response to the immune treatment was also determined by the expression level of PD-L1, tumor mutation burden, EGFR mutation and other unknown factors." (PMID 32209727, 2020). "This could suggest the need for co-targeting of EGFR-associated pathways to prevent tumor progression." (PMID 32316322, 2020). "In terms of predicting the tumor progression risk after EGFR-TKI therapy, clinical decisions based on the DL semantic signature led to better survival outcomes than those based on radiomics signature across all risk probabilities by the decision curve analysis." (PMID 33331920, 2020). "Repeated tumor biopsy and liquid biopsy are two main methods for detecting the EGFR T790M mutation." (PMID 32549388, 2020). "In this context, the deficient interaction between EGFR-mutant tumor cells and host immune system cells leads to low T-cell infiltrate which may impair PD-L1 inducible expression." (PMID 33114576, 2020). "Increasing evidence indicates that TBK1 could regulate the NF-κB signals, which is associated with EGFR-associated drug resistance acquisition in tumor cells." (PMID 31316001, 2019). "It was confirmed that Osimertinib could inhibit the proliferation of tumor cells with EGFR mutation and T790M resistance mutation in zebrafish, which was consistent with the clinical research conclusion." (PMID 31346515, 2019). "Patients with detectable EGFR gene mutations in circulating tumor DNA, which is generally concordant with that of tumor tissue, may have a higher response rate to epidermal growth factor receptor tyrosine kinase inhibitor (EGFR-TKI) than unmutated patients." (PMID 30849971, 2019). "Indeed, the high tumor mutation burden in patients with EGFR-mutant NSCLC was involved in poor prognosis of EGFR-TKIs treatment." (PMID 30875919, 2019). "For NSCLC, NGS-based tumor-profiling multiplex gene panels, such as Oncomine Dx target test or FoundationOne CDx, have recently been approved as companion diagnostics to detect mutations of EGFR and BRAF, or fusions of ALK and ROS1 in the US." (PMID 30943926, 2019).
tumor (continued). "As previously reported, active mutations in EGFR could activate relevant intracellular signaling pathways to enhance tumor glycolysis; consequently, intense 18F-FDG uptake manifestation in PET images was observed." (PMID 31681597, 2019). "Low expression levels of AREG and EREG associated with KRAS mutations might indicate a tumor that is less dependent on EGFR and is therefore particularly prone to developing resistance to anti-EGFR MoAbs." (PMID 31771279, 2019). "The indications of radical surgery differ between metastatic and multiple primary cancers; however, the epidermal growth factor receptor mutation screenings turned out to be discordant, with exon 19 deletion in the right and exon 21 L858R mutation in the left tumour." (PMID 31139414, 2019). "EGFR mutation detection by tumor tissues and matched cell blocks in MPEs." (PMID 31608233, 2019). "The purpose of the present study was to identify the expression patterns of EGFR and its downstream signaling pathway molecules in pituitary corticotroph adenomas and to investigate the association of EGFR with clinicopathological characteristics and tumor recurrence." (PMID 31798535, 2019). "An EGFR amp was found in one tumor (C1030BL) and this associated with prolonged benefit." (PMID 31287991, 2019). "Thus, second-generation EGFR TKIs (e.g. avitinib and dacomitinib) were designed to target tumours with T790M mutation and EGFR-activating mutations." (PMID 31598253, 2019). "Knowledge of the rather low expression of mutated KRAS in the patient’s tumor might have allowed a combinatorial anti-EGFR treatment to potentially improve the outcome." (PMID 31805664, 2019). "Independent of EGFR-mediated MAPK/AKT signaling, PKM phosphorylation was highly ranked in approximately half of our ccRCC tumor cohort and associated with lower tumor grade (p < 0.05), reflecting a secondary, EGFR-mediated mechanism of glycolytic reprogramming in a subset of ccRCC tumors." (PMID 31675502, 2019). "In this study, we measured the expression of five circulating miRNAs (miR-195, miR-504, miR-122, miR-10b and miR-21) in plasma taken from NSCLC patients and evaluated their association with EGFR mutation status in tumour tissue and cfDNA compared to previously reported results." (PMID 30953094, 2019). "The tumor model used in PDX harbors EGFR mutation, as well as PI3KA mutation, which may explain results of inefficient YD single administration group." (PMID 31043587, 2019). "There is no doubt that activation of the tyrosine kinase activity of EGFR, regardless of its mutational status, promotes cell proliferation and tumor growth of experimental models, which has served as the scientific basis supporting the targeting of the kinase activity of EGFR for cancer therapies." (PMID 31508364, 2019). "- Mass spectrometry imaging analysis can visually plot the spatial distribution heterogeneity of EGFR mutation status, which may benefit our understanding of tumor heterogeneity." (PMID 31555581, 2019). "We deduce that the heterogeneous distribution of phospholipids in tumor tissues may be related to the spatial distribution heterogeneity of EGFR mutations." (PMID 31555581, 2019). "Moreover, NSCLC overexpressing wild- type EGFR are often primary resistant, especially in tumor with concurrent KRAS mutation." (PMID 31196210, 2019). "Although CCA is characterized by different tumour biology, EGFR mutation analysis might be of importance for the choice of therapeutic treatment." (PMID 30634942, 2019). "Some mechanisms such as energy balance may attribute to the specific secondary EGFR mutation type in the tumour of familial cases." (PMID 31703574, 2019). "Mechanistically, GPAA1 enhanced the levels of metastasis-associated GPI-anchored proteins to increase tumour metastasis and intensified lipid raft formation, which consequently promoted the interaction between EGFR and ERBB2 as well as downstream pro-proliferative signalling." (PMID 31118109, 2019).
tumor (continued). "Furthermore, increased expression of EGFR can be observed in myeloid cells from the tumor stroma and associates with tumor progression and reduced survival time of patients with gastrointestinal cancers, including colorectal." (PMID 31370270, 2019). "Since hypoxia and Hypoxia Inducible Factor-1 (HIF-1) have been associated with treatment failure and tumor progression, we hypothesized that EGFR/mammalian Target of Rapamycin (mTOR)/HIF-1 axis inhibition could radiosensitize HNSCC." (PMID 31640284, 2019). "Smoking is associated with tumor mutation burden and EGFR mutation status." (PMID 31752884, 2019). "The EGFR mutations detected from these tumors were G719S and R776H mutations from one lesion (#2233–1) and an exon 19 deletion from another (#2233–2), indicating different tumor origins." (PMID 30808329, 2019). "Lack of PTEN protein expression significantly associated with a high risk of progression in the first-line anti-EGFR setting, with a time to progression of 4.2 months versus 9.4 months in patients whose tumours expressed PTEN (HR = 3.7, CI95% 1.1–13.1, p = 0.03)." (PMID 31537838, 2019). "The analysis of circulating tumor DNA (ctDNA) is a valuable approach to monitor the clonal evolution of tumors during treatment and to detect mutations capable of inducing resistance to EGFR-TKIs." (PMID 31039766, 2019). "Importantly, these aberrations can co-occur within the same tumour and co-exist with EGFR tertiary mutations, underlying the complexity and heterogeneity of cancer evolution in response to EGFR-TKI treatment." (PMID 31564718, 2019). "EGFR mutation detection by exosomes in MPEs and matched tumor tissues." (PMID 31608233, 2019). "Conclusions: altogether, our data suggest that resistance to EGFR inhibition combined with radiotherapy in HNSCC may depend on tumor HIF-2 expression and underline the urgent need to develop novel HIF-2 targeted treatments." (PMID 31640284, 2019). "Hence, there are still several open questions about PD-L1 axis inhibitors in patients with NSCLC whose tumors harbor EGFR mutations, such as the effect of EGFR tyrosine kinase inhibitors (TKIs) or EGFR mutations in the tumor microenvironment (TME)." (PMID 31526368, 2019). "Moreover, EGFR-TKIs treatment was effective in patients with sensitive EGFR mutations in either plasma cfDNA or tumor tissue-derived DNA." (PMID 31413754, 2019). "However, routine driver oncogenes detection methods including direct sequencing and ARMS have inherent limitations: lose all spatial distribution information of EGFR mutations during the tumor tissue homogenization process." (PMID 31555581, 2019). "Therefore, the possibility of a new tumor cell clone with loss of EGFR expression in xenografts cannot be excluded." (PMID 31732509, 2019). "Therefore, the expression of FAM83A and B was analyzed in tumor tissue of NSCLC patients with ADC expressing either wild-type EGFR (79 patients) or EGFR signaling activating mutations (29 patients)." (PMID 31083571, 2019). "Besides, the overactivation of the epidermal growth factor receptor (EGFR) signaling pathway by either overexpression or mutation is frequently involved in tumor initiation, growth, and metastasis." (PMID 31300030, 2019). "Because the EGFR inhibitor suppressed CD44v expression even in KRAS-mutated cancer cells, the EGFR inhibitors could also be applicable to the KRAS-mutated tumours to target the drug-tolerant CD44v-positive cancer cells." (PMID 31607750, 2019). "Activating mutations in the EGFR gene were found in 10% of the analyzed human tumor specimens." (PMID 31614493, 2019). "Also, in NSCLC patients with activating EGFR mutation, longitudinal tumor rebiopsy has shown the appearance of p.T709M mutation during chemotherapy treatment." (PMID 30809319, 2019). "Furthermore, discovering common convergent diagnostic and therapeutic themes related to EGFR-TKI resistance is needed for tackling the challenge of tumor heterogeneity." (PMID 31266248, 2019).
tumor (continued). "The assay could be valuable in the detection of actionable EGFR mutations in patients who are unable to undergo repeat biopsies and possibly detecting “missed” mutations by standard tissue genotyping due to tumor heterogeneity." (PMID 31413754, 2019). "Hence, current gene mutations detection methods provided little information of EGFR mutations spatial distribution, were unable to assess the intra-tumor heterogeneity." (PMID 31555581, 2019). "In this respect, responses to first generation EGFR TKIs have been observed in patients carrying both an EGFR sensitizing and the p.T790M mutation when the resistance mutation is expressed in a minor clone of tumour cells." (PMID 30857358, 2019). "Interestingly, circulating miR-504 levels were significantly reduced in the v-Ki-ras2 Kirsten rat sarcoma viral oncogene homolog (KRAS)-mutated subgroup compared to EGFR-mutated patients (p < 0.0030) and those with EGFR/KRAS wild-type tumours (p < 0.0359)." (PMID 30953094, 2019). "For example, specific co-occuring genetic alterations acquired with disease progression (e.g. in CTNNB1 and PIK3CA), were shown to cooperatively promote tumor metastasis, while other evolutionary paths impair the apoptotic response and cause resistance to EGFR inhibitors." (PMID 31139322, 2019). "Some of the tumor subtypes are rare such as squamous tumors that are EGFR mutation positive, and because only study level covariate data were reported we do not know whether all patient types existed in the data analyzed." (PMID 30987609, 2019). "Once activated, tumor associated myeloid cells contribute to tumor proliferation by secreting oncogenic factors such as EGFR, extracellular matrix (ECM) remodeling by releasing proteases such as MMP2 and MMP14 and induction of angiogenesis by secretion of proangiogenic factors." (PMID 32038644, 2019). "Therefore, our data elucidate the mechanism of paradoxical tumor progression upon β-catenin deficiency/inhibition by establishing the connection between the AJ complex and EGFR signaling in HCC." (PMID 31015417, 2019). "Accordingly, dynamic monitoring for the emergence of activation mutations of effectors downstream located in EGFR signaling pathway, especially RAS mutations in patients undergoing anti-EGFR therapies can be a useful tool to determine tumor response and ongoing patient care." (PMID 31253124, 2019). "The tumor also contained two oncogenic missense mutations in EGFR A289V and PIK3CA G118D." (PMID 31258848, 2019). "A previous study by our group demonstrated the presence of EGFR heterogeneity on the tissue level and showed that the relative abundance of EGFR mutation in tumor tissues could predict the benefit of EGFR-TKI treatments." (PMID 31014278, 2019). "For example, Next-generation sequencing (NGS) for concomitant driver mutations was performed on EGFR-mutated tumour samples from erlotinib-treated patients and the result showed that most concomitant mutations (including EGFR/K-RAS) did not impact the response to first-line erlotinib-treatment." (PMID 31739412, 2019). "Moreover, a strong tumor-specific T cell response has the potential to dramatically change the inflammatory environment of the tumor, and support epitope spreading to common mutations shared between EGFRvIII+ and EGFR wt neighbors." (PMID 30601871, 2019). "In the EGFR-Pcn tumor discs, the associated trachea were more extensive and branched than normal." (PMID 31568500, 2019). "In a cis configuration with the activating mutation, T790 M mutation could dramatically enhance EGFR catalytic activity, and thus, achieve a significant gain of function in transformation and tumour aggressiveness." (PMID 31703574, 2019). "This tumor cell population, which is likely negligible at diagnosis, fitting the general view that EGFR mutations are in the genetic trunk of the tumor, could be selected during therapy with EGFR TKI." (PMID 31861832, 2019).